KISS1R (KISS1 receptor)
Diseases named in the same sentence as KISS1R in open-access papers (continued):
Sharing a sentence is not in itself a finding about the gene and the disease.
tumor (continued). "It was reported in tumor cells that the activation of KISS1R could inhibit ERK1/2, which might subsequently lead to the inhibition of the inflammatory transcription factor NF-κB and the collagenase MMP-928." (PMID 37640761, 2023). "Specifically, KISS1R regulates the expression of the transcription factor c-Myc and glutaminase that are necessary for glutamine catabolism and therefore drives processes such as nucleotide synthesis required for tumor growth." (PMID 32034133, 2020). "Taken together, these results reveal that human KISS1R induces primary tumor growth and metastasis." (PMID 32034133, 2020). "We then sought to determine whether KISS1R regulated the glutamine utilization to thereby support tumor growth." (PMID 32034133, 2020). "However, later, the involvement of KISS1/KISS1R in tumor development was demonstrated in several tumor types." (PMID 31336647, 2019). "Decreased expression of KISS1/KISS1R in tumor tissues compared with normal." (PMID 30123188, 2018). "Genomic studies suggest that KiSS-1/KiSS-1R expression might be different in the various stages of tumor development." (PMID 29760678, 2018). "Furthermore, immunolocalization of endogenous KISS1R was found to be enhanced at the leading edge of migratory tumor cells." (PMID 30123188, 2018). "We also found that cells expressing KISS1R in TNBC tumor biopsies also expressed BCRP." (PMID 28422142, 2017). "Besides an autocrine mechanism, paracrine signaling between kisspeptin-expressing tumor cells and KISS1R-expressing stromal cells has also been suggested." (PMID 27158817, 2016). "KISS1R also demonstrates membranous and cytoplasmic staining in ccRCC tumor cell lines (SF5B)." (PMID 24979721, 2014). "As KISS1R, KSR1, CAMK1, and SSPN have been either previously implicated in tumor cell migration or are known to participate in extracellular matrix adhesion, we wanted to explore whether any of these factors mediate RCC cell invasiveness." (PMID 24979721, 2014). "Since KISS1R is a G-coupled protein receptor, these results suggest that KISS1R may be functionally active in tumor samples as compared to normal." (PMID 24979721, 2014). "Previous studies evaluating KISS1R expression and its role in tumorigenesis in ccRCC has emphasized a tumor-suppressive role for this receptor in conjunction with its ligand, kisspeptin, where it inhibits tumor cell invasion." (PMID 24979721, 2014). "Interestingly, KISS1R appears to be predominantly localized to the plasma membrane in the tumor samples at all stages of disease, where staining in the corresponding normal samples was primarily cytoplasmic (SF5A)." (PMID 24979721, 2014). "Thus, contrary to its anti-metastatic role in many tumors, KP/KISS1R might also exhibit pro-metastatic properties, depending on the tumor entity." (PMID 38256878, 2023). "However, it is not known whether plasma levels of KPs change in TNBC and whether KISS1R regulates metastasis or tumor metabolism." (PMID 32034133, 2020). "As normal canine osteogenic progenitor cells appear to possess significantly lower levels of Kiss1R expression, it would seem that tumor cells may selectively up-regulate this receptor, and that Kiss1R signaling is less frequently observed in a normophysiologic context." (PMID 30777054, 2019). "We also found that KISS1R signaling regulates the mRNA and protein expression and secretion of fibulin-3, supporting that fibulin-3 may be a downstream effector of KISS1R signaling; this suggests that KISS1R signaling may influence components of the tumor microenvironment via fibulin-3." (PMID 30046386, 2018). "Furthermore, we demonstrate that antagonizing KISS1R resensitizes tumor cells to chemotherapy." (PMID 28422142, 2017). "Therefore, the KISS1R and kisspeptin represent an intriguing signaling system which is of particular interest in MM where tumor-microenvironment interactions are pivotal to tumor progression." (PMID 27158817, 2016).
tumor (continued). "Furthermore, our data suggests that KISS1R expression only occurs in hypoxic tumor environments after Rb-loss and these parameters were not determined for the tissue specimens in the previous report." (PMID 27015368, 2016). "We first determined the expression of KISS1R, the target of the newly developed [68Ga]KISS1-54 radiotracer in selected human tumor cell lines of different tumor types." (PMID 38256878, 2023). "In TNBC, the overexpression of KISS1R promotes EMT and results in tumor invasion by mediating MAPK and MT1-MMP signaling pathways and activating MMP-9." (PMID 37174125, 2023). "The KISS1 gene product functions as tumor metastasis suppressor and is reported to act after binding with human orphan G protein-coupled receptor (hOT7T175 or GPR54, KISS1R)." (PMID 35117986, 2021). "Recently, we demonstrated that KISS1/KISS1R mRNA and protein expression was upregulated in primary TNBC tumor biopsies compared to healthy breast tissue." (PMID 30123188, 2018). "Results revealed a punctate distribution of KISS1 and a robust localization of KISS1R and AXL in tumor cells." (PMID 28422142, 2017). "These genes, with the exception of KISS1R and NPTX2, were also upregulated in non-tumor samples from RCC-affected kidneys." (PMID 26317980, 2015). "By binding to G-protein-coupled receptor (GPR54/KISS-1R), kisspeptins regulate in addition to tumor metastasis, puberty onset, and fertility through stimulation of gonadotropin and gonadotropin-releasing hormone (GnRH), as well as trophoblast invasion during pregnancy." (PMID 37360514, 2023). "This study reveals that KISS1R signaling plays a central and multifunctional role in ERα-negative breast cancer, by supporting tumor growth and metastasis." (PMID 32034133, 2020). "However, when breast cells lose ERα, KISS1R signaling promotes epithelial-to-mesenchymal-transition (EMT) and stimulates tumor invasion by inducing invadopodia formation via MT1-MMP and the mitogen-activated protein kinase (MAPK) pathway." (PMID 32034133, 2020). "Thus, KISS1R expression was depleted in metastatic MDA-MB-231 cells and tested for its effect on tumor growth and metastasis in a spontaneous metastasis xenograft model using NOD/SCID/IL2 receptor γnull mice." (PMID 32034133, 2020). "In fact, it has been demonstrated that KISS1 and KISS1R expression in tumor cells is not sufficient, per se, to predict cancer development behavior." (PMID 31336647, 2019). "Thus, in the tumor microenvironment, we should evaluate not only the expression of KISS1/KISS1R in surrounding cells, but also in additional regulation systems such as in the production of cytokines." (PMID 31336647, 2019). "Whether KISS1, KISS1R and fibulin-3 are expressed in the TNBC tumor microenvironment has yet to be determined." (PMID 30046386, 2018). "First, the lack of KISS1R expression in many tumor cell lines that can be metastasis suppressed by re-expression of KISS1 provided the first clue that autocrine signaling is not required for an anti-metastatic function." (PMID 24454770, 2014).
cancer (36 papers, 2007 to 2026). A tumor composed of atypical neoplastic, often pleomorphic cells that invade other tissues. "KISS-1R encodes for the KiSS1-derived peptide receptor, a G-protein-coupled receptor which is known to play multiple roles in cancer development and metastasis." (PMID 24887580, 2014). "Targeting KISS1R holds great promise for molecular imaging and targeted radionuclide therapy of aggressively disseminated cancers." (PMID 41774810, 2026). "Kisspeptins (KPs, KISS1) and their receptor (KISS1R) play a pivotal role as metastasis suppressor for many cancers." (PMID 38256878, 2023). "Kisspeptin is a known metastasis suppressor that triggers wide signal transduction downstream after binding to its G protein-coupled receptor KISS1R, leading to a suppression of metastasis in most cancer types." (PMID 38256878, 2023). "KISS1R has been found largely in many human cancers, while its expression in most healthy tissues is relatively low." (PMID 38256878, 2023). "Kisspeptin is an anti-metastatic mediator in many cancer types, acting through its receptor, KISS1R." (PMID 35955878, 2022). "In these cancers, KISS1R signalling suppresses metastasis by repressing MMP-9 activity, thereby inhibiting cancer cell invasion and migration." (PMID 35955878, 2022). "Kisspeptin/KISS1R has been shown to suppress metastasis in many cancer types, including melanoma, colorectal cancer, bladder cancer, lung cancer, prostate cancer, ovarian cancer, and pancreatic cancer." (PMID 35955878, 2022). "With several reports studying the expression and function of Kp and its receptor, KISS1R, in cancer and other disease models, our study showed, for the first time, robust expression and function of Kp/KISS1R in human ASM." (PMID 35883681, 2022). "In the future, additional experiments will be required to explore the role of KISS1 and KISS1R in other cancers and to determine the exact mechanism of their function." (PMID 35117986, 2021). "Given their roles, KISS1, KPs and KISS1R represent important molecules in the development of novel therapies and/or as prognostic markers in treating cancer." (PMID 30123188, 2018). "The authors also compared KISS1R mRNA levels in cancer and matched normal tissues from each patient (n = 5) and found that the receptor expression was higher in cancer tissue compared to the adjacent normal in all paired samples." (PMID 30123188, 2018). "KiSS1 and its receptor KiSS1R have been studied for their metastasis-suppressing ability in numerous human cancer cells." (PMID 27287327, 2016). "On the other hand, downregulated GPCR, GPR54 (also called KISS1R), has been shown to be a metastasis suppressor in numerous cancers in humans." (PMID 23383159, 2013). "Little is known on the potential role of the other two hypoxia inducible genes, ZNF395 and KISS1R, in cancer." (PMID 19536297, 2009). "Several studies have described a prognostic value of KISS1 and KISS1R expression in tumors across a variety of cancer types and a role in metastasis and trophoblast invasion, both invasive processes." (PMID 19536297, 2009). "KISS1R is the gene for a metastasis suppressor protein, whose downregulation in s-μg may be involved in the observed in vitro metastasis of cancer cells on the RPM." (PMID 40001606, 2025). "KISS1 or KISS1R is likely to be an independent prognostic factor in certain cancer types." (PMID 35117986, 2021). "In particular, they assessed that the expression levels of KiSS-1 and KiSS-1R were lower in cancer tissues compared to normal tissues; moreover, KiSS-1 and KiSS-1R expression was lower in patients with advanced stage compared to patients with low stage of NSCLC." (PMID 29760678, 2018). "In this review, we focused on multiple functions exerted by the KPs/KiSS-1R system in cancer." (PMID 29760678, 2018). "However, therapeutic programs using KISS1 agonists to modulate KISS1R-expressing neurons likely activate KISS1/KISS1R signaling in individual cancer cells." (PMID 27015368, 2016).
cancer (continued). "However, KISS1R signaling in cancer appears to be context specific." (PMID 35349482, 2022). "Consistently, in vitro, Kp-13 also modulates via Kiss1R, the contractions of circular and longitudinal colonic muscle promoting gastrointestinal motility, whereas, the anti-metastatic effects of kisspeptin just occur through the inhibition of cancer cells motility and invasion ability." (PMID 35205340, 2022). "Nevertheless, the dynamics between KPs and KISS1R need to be further investigated to fully harness the radiotheranostic potential of KISS1R for TNBC and other cancers." (PMID 41774810, 2026). "KISS1R binds kisspeptins, peptide products of the KISS1 gene and in numerous cancers, this signaling pathway plays anti-metastatic roles." (PMID 28422142, 2017). "Conventional target detection methods using antibodies (Abs) and AF-488-KPs failed to visualize KISS1R in both model (CHO-KISS1R) and native cancer cell lines, likely due to unspecific Abs and rapid KISS1R internalization upon agonist stimulation." (PMID 41774810, 2026). "An interesting study showed that the antiproliferative effects of kisspeptin reported by some studies were mainly due to the exogenous overexpression of KISS1R, while cancer cell lines with endogenous KISS1R expression only did not respond to KP-10 to alter their proliferation rate." (PMID 35955878, 2022). "In native TNBC cells lacking ERα, KISS1R signaling promotes epithelial-mesenchymal transition, MAPK activation, and cancer growth and invasion." (PMID 35349482, 2022). "Therefore, in ERα-negative cancers such as TNBC, this may partly account for the switching of KISS1R from metastasis suppressor to promoter." (PMID 32034133, 2020).
reproductive diseases (2 papers, 2019 to 2022). "A comprehensive understanding of the expression, function, and potential molecular mechanisms of kisspeptin/KISS1R in the peripheral reproductive system will contribute to the diagnosis, treatment and prevention of reproductive diseases." (PMID 31399145, 2019). "Here, we summarize recent advances in our understanding of the physiological significance of kisspeptin/KISS1R in the peripheral reproductive system (including the ovary, testis, uterus, and placenta) and the potential role of kisspeptin/KISS1R in reproductive diseases." (PMID 31399145, 2019). "In this review, we focus on the local expression and regulation of kisspeptin and its receptor KISS1R in the peripheral reproductive system, including in the ovary, testis, uterus, and placenta, and highlight the potential role of kisspeptin/KISS1R in reproductive diseases." (PMID 31399145, 2019). "In conclusion, a complete understanding of the expression, function, and potential molecular mechanisms of kisspeptin/KISS1R in the HPG axis and its role in reproduction will bring new inspiration to the diagnosis, treatment and prevention of some reproductive diseases." (PMID 35837314, 2022).
adenocarcinoma (1 paper, 2017). A common cancer characterized by the presence of malignant glandular cells. "Also, we did not observe an association between KISS1R mRNA expression in adenocarcinoma and improved survival." (PMID 29371917, 2017).
neurological disease (1 paper, 2016). "Analysis of the neurological disease network identified several key up-regulated targets such as HTR5A, KISS1R and GPR146." (PMID 27015368, 2016).
KISS1R also shares sentences with these, for which no sentence is quoted: pancreatic cancer (6 papers); type 2 diabetes (4); Anxiety (2); endocrine disorder (2); endometrial cancer (2); fibrosis (2); gastric cancer (2); lymph node metastasis (2); multiple myeloma (2); ovarian failure (2); abortion (1); androgenic alopecia (1); aneurysm (1); Anosmia (1); anovulation (1); atherosclerosis (1); cardiac interstitial fibrosis (1); cardiovascular disease (1); cerebral aneurysms (1); CHARGE syndrome (1); clear cell carcinoma (1); clear cell ovarian cancers (1); craniofrontonasal syndrome (1); cryptorchidism (1); Epididymis (1); esophageal squamous cell carcinoma (1); gestational diabetes mellitus (1); giant cell tumor (1); hair disorders (1); hair loss (1).
A further 31 diseases each share a sentence with KISS1R in 1 paper.